BRMS1 (BRMS1 transcriptional repressor and anoikis regulator)
Diseases named in the same sentence as BRMS1 in open-access papers (continued):
Sharing a sentence is not in itself a finding about the gene and the disease.
cancer (35 papers, 2010 to 2026). A tumor composed of atypical neoplastic, often pleomorphic cells that invade other tissues. "Recent clinical studies have confirmed that the expression of BRMS1 is reduced in a variety of malignant tumors, which seems to be associated with the invasion and metastasis of cancer cells and a better prognosis for patients." (PMID 39143438, 2024). "The analysis of human NSCLC specimens confirmed that CK2α’ and cytoplasmic BRMS1 expression levels in cancer tissues are associated with increased tumor recurrence, metastatic foci, and reduced disease-free survival." (PMID 36009534, 2022). "However, a detailed underlying mechanism by which BRMS1 attenuates cancer cell EMT and invasion remained to be answered." (PMID 26520789, 2015). "In humans, BRMS1 inhibits cancer metastasis by modulating signaling pathways that control cell migration, adhesion, and proliferation." (PMID 42082997, 2026). "BRMS1 is a metastasis suppressor gene that inhibits the spread of cancer cells to other parts of the body." (PMID 41203700, 2025). "Under hypoxic stress conditions, cancer cells dependent on BRMS1 exhibit increased sensitivity to anoikis, with a decreased survival rate." (PMID 39143438, 2024). "The metastatic suppressor BRMS1 interacts with critical steps of the metastatic cascade in many cancer entities." (PMID 37296870, 2023). "Of importance concerning the inhibition of cancer metastasis is the Breast cancer metastasis suppressor 1 (BRMS1)." (PMID 36009534, 2022). "BRMS1 is among the promising anti-metastatic breastcancer genes which selectively suppresses metastasiswithout suppression of any cancer cell tumorigenicity.Pleiotropically acting BRMS1 prevents multiple stepsof the metastatic cascade." (PMID 34096224, 2021). "One of the mostapplicable members of metastasis suppressor family, which has a great potential ofmetastasis inhibition, is the breast cancer metastasis suppressor 1(BRMS1)." (PMID 34096224, 2021). "The recent reports haveshown that BRMS1 remarkably suppressed migrationand invasion of cells in many types of cancer." (PMID 34096224, 2021). "hTC and Brms1 show slightly less cancer specificity but higher expression levels, with hTC showing the highest expression levels." (PMID 31039796, 2019). "hTC and Brms1 show higher transfection and expression levels with some cancer specificity, making them ideal for lowering toxicity in order to increase dose without as much of a reduction in the number of cancer cells expressing the gene construct." (PMID 31039796, 2019). "Other groups have tested a variety of lengths of the hTERT promoter in various types of cancer, and the Ran and Brms1 promoters have been shown to be successful in several different cell lines." (PMID 31039796, 2019). "Accumulating evidence suggests two important mechanisms for suppression of BRMS1-induced cancer metastasis: interaction with chromatin remodeling and inhibition of nuclear factor-kappaB (NF-κB) activity." (PMID 26520789, 2015). "Collectively, the present study demonstrates a mechanical cascade of BRMS1 suppressing cancer cell invasion through downregulating HIF-1α transcript and consequently reducing Snail and TWIST1 expression." (PMID 26520789, 2015). "It follows that SIN3A:BRMS1 complexes are likely regulated by the environments surrounding cancer cells." (PMID 23390556, 2013). "Breast cancer metastasis suppressor 1 (BRMS1) is a predominantly nuclear protein that suppresses metastasis in multiple human and murine carcinoma cell lines." (PMID 23390556, 2013). "Low BRMS1 expression levels have been detected in cell lines and tissue specimens from various human cancers." (PMID 22931099, 2012). "BRMS1 has also been shown to reduce the capacity of multiple human cancer cell lines to metastasize to the lymph nodes, lungs and/or bone in experimental models." (PMID 22200669, 2012).
cancer (continued). "As expected, the patients with low BRMS1 expression experienced more metastasis during the follow-up period compared to those with high BRMS1 expression, suggesting that BRMS1 can suppress cancer metastasis in NPC patients." (PMID 22931099, 2012). "We show for the first time that fascin down-regulates the expression and nuclear translocation of a key metastasis suppressor protein known as breast cancer metastasis suppressor-1 (BRMS1)." (PMID 22076152, 2011). "In vitro, over-expression of BRMS1 decreased cancer cell survival under hypoxic stress, decreased the adhesion ability of cancer cells and increased apoptosis." (PMID 20195375, 2010). "BRMS1 plays a central role mainly in the inhibition of cancer metastasis." (PMID 37032832, 2023). "BRMS1 interacts with critical steps of the metastatic cascade in many cancer entities." (PMID 37296870, 2023). "Furthermore, it has been shown that the metastatic suppressor, BRMS1, increases the level of miR-146a in cancer cells to reduce their metastatic potential." (PMID 33248456, 2020). "The hTC (2nd set of bars) and Brms1 (last set of bars) promoters also displayed cancer specificity in the form of significantly higher GFP expression in all cancer cells when compared with normal BJ cells, while − 279/+ 5 and Ran showed specificity in Skov3 and Ovcar3 but not Kuramochi cells." (PMID 31039796, 2019). "The other common MS genes, including CD28, KISS1, NME2, BRMS1, shared in over 10 cancer types." (PMID 26486520, 2015). "Therefore, our results identify mechanism by which BRMS1 attenuates cancer cell progression through downregulating HIF-1α and subsequently reducing Snail and TWIST1 expression." (PMID 26520789, 2015). "This differs from what has been published regarding BRMS1 mRNA levels in other cancers." (PMID 24688598, 2014). "Some studies have shown that the BRMS1 promoter is methylated in many cancers, which might contribute to low BRMS1 expression." (PMID 22931099, 2012). "Since BRMS1 is a metastasis suppressor in many types of cancer, we hypothesize that NPC progression, especially NPC metastasis, may be related to BRMS1 levels." (PMID 22931099, 2012). "It is also possible that fascin and BRMS1 have a feedback loop where BRMS1 may also down-regulate fascin to inhibit cancer cells from metastasis." (PMID 22076152, 2011). "Though the cancer-specific function of the Brms1 promoter may be somewhat surprising considering Brms1’s anti-tumorigenic function, if a cancer cell has not managed to mutate the Brms1 pathway then high Brms1 activity is logical." (PMID 31039796, 2019). "This may be counter-balanced by the higher expression levels seen from Brms1 and hTC driven constructs, however—in practice it may be more practical to use a therapeutic that is slightly less specific but more likely to be expressed in more cancer cells." (PMID 31039796, 2019). "However, detailed underlying mechanism by which BRMS1 attenuates cancer cell EMT has not been fully characterized." (PMID 26520789, 2015). "However, there is some disagreement on the role of BRMS1 in cancer." (PMID 22931099, 2012). "Furthermore, BRMS1 differentially regulates cancer cell responses to growth factor signaling." (PMID 22356677, 2012). "All of the functional studies above demonstrate the inhibitory effects of BRMS1 on NPC metastasis, which is consistent with reports on its effects in other cancers." (PMID 22931099, 2012). "Ran and Brms1, along with hTC and − 279/+ 5, were tested for GFP expression levels in the same four cell lines as before, and once again hTC showed higher expression levels than any other cancer-specific promoter in all four cell lines (2nd bar)." (PMID 31039796, 2019). "Even if the BRMS1-iASPP-p300/CBP-TAp73 axis proved to be difficult to target, it may nonetheless provide prognostic or predictive markers for cancer progression." (PMID 25675294, 2015).
cancer (continued). "Although the clinical significance of BRMS1 in many cancers has been established, the mechanisms by which BRMS1 expression is decreased in tumors is still not clear." (PMID 22931099, 2012).
adeno-carcinoma (1 paper, 2021). "We found that re-expression of BRMS1 in the context of anexpeditiously designed gene delivery vehicle may decline the ability of migration andinvasion of metastatic adeno-carcinoma cells." (PMID 34096224, 2021).
infection (1 paper, 2012). The state of being infected such as from the introduction of a foreign agent such as serum, vaccine, antigenic substance or organism. "Additional LO infection exerted no obvious effect on cell growth under normal culture conditions; however, after serum deprivation, knockdown of endogenous OPN expression (LS1+LO) significantly eliminated cell growth advantages induced by BRMS1 silencing (LS1)." (PMID 22927944, 2012).
BRMS1 also shares sentences with these, for which no sentence is quoted: prostate carcinoma (2 papers); uveal melanoma (2); Acute myeloid leukaemia (1); ductal carcinoma (1); glioblastoma (1); hypopharyngeal cancer (1); lobular carcinoma (1); lung adenocarcinoma (1); Lung squamous cell carcinoma (1); medullary carcinoma (1); ovarian neoplasm (1); ovarian serous adenocarcinoma (1); pancreatitis (1); papillary renal cell carcinoma (1); rectal cancer (1).